MAGEE1 (MAGE family member E1)
Description:
May enhance ubiquitin ligase activity of RING-type zinc finger-containing E3 ubiquitin-protein ligases. Proposed to act through recruitment and/or stabilization of the Ubl-conjugating enzyme (E2) at the E3:substrate complex.
Synonyms: DAMAGE; HCA1; KIAA1587
Tractability: Antibody: UniProt places it where antibodies can reach, with medium confidence; its Gene Ontology location is reachable by antibodies, with medium confidence. PROTAC: ubiquitination databases record sites on it; its protein half-life has been measured.
Gene: Protein-coding gene on chromosome X (76,427,710 to 76,431,342, forward strand). Ensembl gene ENSG00000198934.
Subcellular location: Cytoplasm, perinuclear region; Nucleus; Cell membrane
Subcellular location (Human Protein Atlas): Cytosol; Cytokinetic bridge
Gene Ontology:
Molecular function: protein binding
Biological process: negative regulation of transcription by RNA polymerase II
Cellular component: dendrite; nucleus; perinuclear region of cytoplasm; plasma membrane; postsynaptic membrane
Homologues: Orthologues: chimpanzee MAGEE1 (99% identical), macaque MAGEE1 (89% identical), guinea pig MAGEE1 (64% identical), rat Magee1 (63% identical), mouse Magee1 (61% identical), zebrafish ndnl2 (9% identical), Drosophila melanogaster MAGE (7% identical). Paralogues in human: TRO (15% identical), MAGEL2 (15% identical), MAGED1 (15% identical), MAGED2 (15% identical), MAGEE2 (14% identical), MAGEB16 (14% identical), MAGEB4 (14% identical), MAGEA10 (14% identical), MAGEB1 (14% identical), MAGED4 (14% identical), MAGED4B (14% identical), MAGEB10 (13% identical), and 25 more.
Diseases named in the same sentence as MAGEE1 in open-access papers:
MAGEE1 is named in the same sentence as 12 diseases in open-access papers, as found by Europe PMC text mining. Sharing a sentence is not in itself a finding about the gene and the disease. The quoted sentences say what the papers report.
melanoma (4 papers, 2010 to 2023). A malignant, usually aggressive tumor composed of atypical, neoplastic melanocytes. "MHD of MAGEE1 is frequently mutated in both melanoma and OCCC and is predicted to be damaging." (PMID 34006971, 2021). "MHC-I AI alleles also uniquely target positions in the melanoma antigen genes MAGEA10 and MAGEE1, which are upregulated in melanoma relative to melanocytes." (PMID 37339630, 2023). "We undertook a mutational analysis of coding regions of four CT-X MAGE genes, MAGEA1, MAGEA4, MAGEC1, MAGEC2 and the ubiquitously expressed MAGEE1 in human melanoma samples." (PMID 20862285, 2010). "Evaluating expression in melanomas relative to melanocytes, we observed that two MAGE genes, MAGEA10 and MAGEE1 (MIM: 300759), were significantly upregulated and that several canonical melanocyte and stably expressed genes were downregulated." (PMID 37339630, 2023).
glioma (3 papers, 2020 to 2022). A benign or malignant brain and spinal cord tumor that arises from glial cells (astrocytes, oligodendrocytes, ependymal cells). "For example, MAGEE1 was associated with important clinical and molecular features in glioma, and can be considered an important marker in determining the prognosis of glioblastoma." (PMID 35321944, 2022). "Further, other downregulated T2Ms in glioma, including MAGEE1, MAGEL2, TRO, and NDN also exhibited similar negative correlations with immune cell infiltration in LGG, while in GBM they showed a varying degree of positive correlations with infiltration of different immune cells." (PMID 33425727, 2020). "This analysis revealed that some MAGEs including MAGED subfamily are overexpressed, while most others including MAGEE1, MAGEE2, MAGEL2, MAGEH1, NDN, and TRO are downregulated in glioma." (PMID 33425727, 2020).
breast carcinoma (2 papers, 2024 to 2026). "Furthermore, MAGEE1 is frequently mutated and considered a candidate cancer gene in breast cancer, WWC3 has a high potential for complete or partial escape in ovarian cancer, and HUWE1 is known as a tumor suppressor gene." (PMID 41522471, 2026). "A number of X‐linked cancer‐related genes, including FLNA, PFC, PRPS1, TARD8, MAGEE1, TAF, and KLH4 have been associated with breast cancer." (PMID 38827026, 2024). "The X‐linked cancer‐related genes FLNA, PFC, PRPS1, TARD8, MAGEE1, TAF, and KLH4 have all been associated with breast cancer." (PMID 38827026, 2024).
leukemia (1 paper, 2024). A malignant (clonal) hematologic disorder, involving hematopoietic stem cells and characterized by the presence of primitive or atypical myeloid or lymphoid cells in the bone marrow and the blood. "We first analysed the DA1-3b leukemia model and among the 70 commonly mutated genes in dormant leukemia DA1-3b/D365 and parental DA1-3b cells, ten genes (Ttc7b, Dnmt3b, Ap1b1, Ne1, Nedd4, Acy1, Cyp11a1, Htr2c, Magee1 and Gdi1) were amplified in dormant and parental cells." (PMID 39223638, 2024).
tumor (7 papers, 2020 to 2026). "The APA patient carrying this variant had enormous plasma aldosterone levels (1180 ng/l) and a larger tumor (40-mm diameter), suggesting that a loss of antiproliferative effect of MAGEE1 leads to a larger tumor and produces higher aldosterone." (PMID 34006971, 2021). "More importantly, the expression of MAGEE1 is correlated with tumor-cell proliferation of NSCLC." (PMID 35321944, 2022).
cancer (6 papers, 2010 to 2026). A tumor composed of atypical neoplastic, often pleomorphic cells that invade other tissues. "Furthermore, MAGEE1 was mutated sufficiently frequently to be classified as a candidate cancer gene (CAN-gene) in breast cancer and thus potentially a driver of tumorigenesis." (PMID 20862285, 2010). "MageE1, a cancer-testis antigen (CTA), was expressed at significantly higher levels in KP-LC compared to KPL 160424S and as previously, genes differentially expressed by KP-LC and KPL 160424S were enriched in several pathways associated with cancer." (PMID 32903551, 2020).
infection (1 paper, 2021). The state of being infected such as from the introduction of a foreign agent such as serum, vaccine, antigenic substance or organism. "Neuronal signaling and repair genes MAGEE1 and LPAR1 also follow similar patterns of expression at each time point and are significantly elevated in BALB/c mice at each stage of infection." (PMID 33816350, 2021).
MAGEE1 also shares sentences with these, for which no sentence is quoted: glioblastoma (2 papers); clear cell carcinoma (1); Liver Cirrhosis (1); ovarian carcinoma (1); ovarian clear cell cancer (1).